ENKD1 (enkurin domain containing 1)
Description:
Microtubule-binding protein which regulates microtubule organization and stability. Promotes the stability of astral microtubules and facilitates the proper orientation of the mitotic spindle. This allows the oriented division of basal keratinocytes and contributes to epidermal stratification (By similarity). Required for the assembly of both primary and motile cilia. Destabilizes the interaction between CCP110 and CEP97 by competing with CEP97 for binding to CCP110 which promotes the removal of CCP110 and CEP97 from the mother centriole and allows the initiation of ciliogenesis.
Synonyms: C16orf48; DKFZP434A1319; FBB11; DAKV6410
Tractability: Antibody: its Gene Ontology location is reachable by antibodies, with high confidence. PROTAC: ubiquitination databases record sites on it.
Gene: Protein-coding gene on chromosome 16 (67,662,945 to 67,667,265, reverse strand). Ensembl gene ENSG00000124074.
Subcellular location: Cytoplasm, cytoskeleton, microtubule organizing center, centrosome; Cytoplasm, cytoskeleton, microtubule organizing center, centrosome, centriole; Cytoplasm, cytoskeleton, cilium basal body; Cell projection, cilium; Cytoplasm, cytoskeleton, spindle; Cytoplasm, cytoskeleton, spindle pole; Cytoplasm, cytoskeleton, cilium axoneme
Subcellular location (Human Protein Atlas): Basal body; Centrosome; Plasma membrane; Primary cilium
Gene Ontology:
Molecular function: alpha-tubulin binding; microtubule binding; protein binding
Biological process: establishment of mitotic spindle orientation; non-motile cilium assembly; motile cilium assembly
Cellular component: centriole; centrosome; ciliary basal body; cilium; cytoplasmic microtubule; microtubule cytoskeleton; 9+0 non-motile cilium; axoneme; ciliary base; spindle; spindle pole
Genetic constraint (gnomAD): Loss-of-function variants: 39 observed, 34.56 expected, observed/expected ratio (o/e) 1.13, 90% interval 0.87 to 1.47. The upper end of that interval is the gene's LOEUF score, 1.47, which puts it in group 6 of 6, group 1 being the genes least tolerant of losing a copy. Missense variants: 474 observed, 458.14 expected, observed/expected ratio (o/e) 1.03, 90% interval 0.96 to 1.12. Synonymous variants: 205 observed, 192.82 expected, observed/expected ratio (o/e) 1.06, 90% interval 0.95 to 1.19.
Homologues: Orthologues: chimpanzee ENKD1 (95% identical), macaque ENKD1 (91% identical), dog ENKD1 (89% identical), pig ENKD1 (89% identical), rat Enkd1 (86% identical), guinea pig ENKD1 (85% identical), mouse Enkd1 (84% identical), rabbit ENKD1 (82% identical), zebrafish enkd1 (50% identical), tropical clawed frog enkd1 (50% identical), Drosophila melanogaster CG11125 (22% identical). Paralogues in human: ENKUR (12% identical).
Diseases named in the same sentence as ENKD1 in open-access papers:
ENKD1 is named in the same sentence as 5 diseases in open-access papers, as found by Europe PMC text mining. Sharing a sentence is not in itself a finding about the gene and the disease. The quoted sentences say what the papers report.
diffuse large B-cell lymphoma (1 paper, 2025). "ENKD1 also plays a part in the regulation of tumor development, including in non-small cell lung cancer and diffuse large B-cell lymphoma." (PMID 40155750, 2025).
ENKD1 also shares sentences with these, for which no sentence is quoted: corneal diseases (1 paper); myopia (1); non-small cell lung carcinoma (1); tumor (1).